MSH6 (mutS homolog 6)
Diseases named in the same sentence as MSH6 in open-access papers (continued):
Sharing a sentence is not in itself a finding about the gene and the disease.
hereditary nonpolyposis colorectal cancer (continued). "This, for instance, is shown for a 20 base pair duplication in MSH6, one of the four mismatch repair genes causing the LYNCH syndrome (HNPCC or hereditary nonpolyposis colorectal cancer), an autosomal-dominant genetic cancer syndrome with a high risk of colon cancer (among others)." (PMID 27220521, 2016).
colon carcinoma (68 papers, 2005 to 2025). "In subject 2, OncoPanel testing on DNA extracted from colon cancer biopsy identified three somatic variants in MSH6: MSH6:c.3253_3254insC, MSH6:c.3556+2T>C, and MSH6:c.3173A>T." (PMID 36091175, 2022). "In this case report, Turcot’s syndrome type 1 harboring the germline mutation of MLH1 with loss of immunoexpression of MSH6 in colon cancer and liver metastasis due to secondary somatic mutation in coding mononucleotide tract in MSH6 is presented." (PMID 32611331, 2020). "MSH6 mutations have been linked to an overall lower risk of colon cancer, less striking family history, higher age at onset and less pronounced tumor morphology, which implies that many cases may escape detection." (PMID 24341444, 2013). "Besides the MSH6 mutation, the neoadjuvant treatment in case 5 could be in some part responsible for the partial loss of MSH6 expression in this colon cancer case." (PMID 36387226, 2022). "Among MMR-associated genes, MSH6 and PMS2 were significantly more frequently mutated in CDX2-suppressed colon cancers, and the same was true for mutations in the proofreading polymerases POLE and POLD1 genes." (PMID 39452477, 2024). "In the reported DL results, a positive fraction of 5 % was used as threshold to assess the presence of PMS2 and MSH6 in colon cancer." (PMID 39040241, 2024). "The IHC staining of the colon biopsy showed deficiency for PMS2 (Subject 1) and MSH6 (Subject 2) proteins, with intact status for other MMR proteins, a pattern consistent with LS-associated colon cancer with germline involvement as a first hit." (PMID 36091175, 2022). "MSH6-A25S was found in a typical LS tumor, i. e., a colon tumor showing MSI, loss of heterozygosity of MSH6, and loss of MSH6 protein expression." (PMID 28531214, 2017). "Both colon cancer cell lines are mutated for MMR, although on different genes (MLH1 and MSH6 for HCT-116 and HCT-15, respectively)." (PMID 23300565, 2012).
colon carcinoma (continued). "The discovery of this patient was through multigene panel testing based on his early-onset colon cancer diagnosis with lack of MSI-H in the tumor despite partial loss of MSH6 expression." (PMID 38243056, 2024). "MGPT was performed after her colon cancer had negative IHC staining for MSH6, and confirmed a germline mutation in MSH6, while revealing additional mutations in BAP1 and RECQL4 genes." (PMID 33541411, 2021). "The same result was obtained from DNA extracted from colon tumor tissue from a cousin (II:6) of our index case who was not a carrier of the MSH6 mutation." (PMID 28481244, 2017). "Details about the extra colonic cancers observed in the MSH6 patient cohort (n = 78)." (PMID 20487569, 2010). "This case supports a plausible mechanism, proposed by a previous literature, for the reduced expression of MSH6 in a somatic mutation manner, which might preferentially happen in colon cancer rather than in stomach carcinoma in MLH1/PMS2-deficient type of Turcot’s syndrome type 1." (PMID 32611331, 2020). "Patient PGT-M4 also had laparoscopic radical resection of colon cancer without chemotherapy in 2017 and was tested for MLH1:c.755C>A and MSH6:c.4065_4066insTTGA mutations, both pathogenic genetic variant." (PMID 38800375, 2024).
colon carcinoma (continued). "The high MF of these clones of DLD1 is due to the defect in the MSH6 MMR gene of this cell line, and similarly, high MF of DLD1 or other MSI colon cancer cells compared with normal diploid fibroblasts has been reported elsewhere using the HPRT or ouabainR endogenously expressed gene systems." (PMID 17285135, 2007).
prostate carcinoma (46 papers, 2010 to 2025). A carcinoma that arises from epithelial cells of the prostate gland. "When repeating analyses for pathogenic variants in four additional genes (BRCA1, RAD50, MLH1, and MSH6) with weaker evidence of association with prostate cancer risk, the risk modifying effect of PRS was similar, albeit the associations were diminished." (PMID 38014910, 2023). "Cluster B included PTEN, a common mutation in mCRPC, and MSH6, a mismatch repair gene seen in 1% of prostate cancer cases." (PMID 38050021, 2023). "This phenotype was subsequently observed in primary prostate cancer in a tumour that harboured an MSH6 mutation." (PMID 25255306, 2014). "In addition, the hypermutated subtype of prostate cancer is chiefly due to loss-of-function mutations in MSH6 in advanced prostate cancer." (PMID 28403887, 2017). "We therefore conclude that the private mutation in MSH6 may have led to spatial MSI and a consecutively increased mutation rate, which is in line with a study on prostate cancer, where somatic mutations in MSH6 have been associated with hypermutation." (PMID 28146430, 2017). "This participant also has a p.E546G VUS in MSH6, a known prostate cancer gene, which is still classified as a VUS at the time of the study." (PMID 38619781, 2024). "In prostate cancer, overexpression of MSH6, MLH1 and PMS2 proteins associates with poor disease outcome and genetic instability in a cohort of 11,152 prostate cancer patients." (PMID 36482191, 2023). "MSH6, a gene implicated in MMR and microsatellite stability, was mutated in both alleles in 7 out of 342 HMF prostate cancer patients." (PMID 36883553, 2023).
prostate carcinoma (continued). "Although the recruitment of men with these rare variants was challenging, particularly for MSH6 carriers, we detected a significantly higher risk of prostate cancer in this cohort than in non-carrier controls." (PMID 34678156, 2021). "We thus hypothesized that transcriptionally-repressed MSH6 gene might be related to H3K27me3 epigenetic modification in prostate cancer." (PMID 28403887, 2017). "This variant is an eQTL for increased expression of MSH6 in many tissues, including nerve, is associated with increased expression of MSH6 in patients with LGG (p = 0.00732), and has previously been reported to be associated with a decreased risk of prostate cancer." (PMID 32066500, 2020). "Furthermore, MSH6 gene was found to be epigenetically regulated in prostate cancer." (PMID 28403887, 2017).